FGF3 (fibroblast growth factor 3)
Description:
Plays an important role in the regulation of embryonic development, cell proliferation, and cell differentiation. Required for normal ear development.
Synonyms: HBGF-3; INT2
Tractability: Antibody: UniProt places it where antibodies can reach, with high confidence; its Gene Ontology location is reachable by antibodies, with high confidence; UniProt predicts a signal peptide or a membrane-spanning region.
Gene: Protein-coding gene on chromosome 11 (69,809,968 to 69,819,416, reverse strand). Ensembl gene ENSG00000186895.
Subcellular location: Secreted
Pathways (Reactome):
Signal Transduction: Downstream signaling of activated FGFR1; FGFR1b ligand binding and activation; FGFR2b ligand binding and activation; FGFRL1 modulation of FGFR1 signaling; FRS-mediated FGFR1 signaling; FRS-mediated FGFR2 signaling; Negative regulation of FGFR1 signaling; Negative regulation of FGFR2 signaling; PI-3K cascade:FGFR1; PI-3K cascade:FGFR2; PI3K Cascade; PI5P, PP2A and IER3 Regulate PI3K/AKT Signaling; PIP3 activates AKT signaling; Phospholipase C-mediated cascade: FGFR1; Phospholipase C-mediated cascade; FGFR2; RAF/MAP kinase cascade; SHC-mediated cascade:FGFR1; SHC-mediated cascade:FGFR2
Disease: Activated point mutants of FGFR2; Constitutive Signaling by Aberrant PI3K in Cancer; Signaling by FGFR2 in disease
Gene Ontology:
Molecular function: protein binding; fibroblast growth factor receptor binding; growth factor activity
Biological process: fibroblast growth factor receptor signaling pathway; negative regulation of cardiac muscle tissue development; positive regulation of cell population proliferation; anatomical structure morphogenesis; cell-cell signaling; neurogenesis; positive regulation of MAPK cascade; regulation of cell migration; signal transduction; regulation of developmental process; regulation of multicellular organismal process
Cellular component: cytoplasm; extracellular region
Genetic constraint (gnomAD): Loss-of-function variants: 7 observed, 6.42 expected, observed/expected ratio (o/e) 1.09, 90% interval 0.61 to 1.82. That is too few expected variants to judge how well the gene tolerates losing a copy. Missense variants: 390 observed, 297.8 expected, observed/expected ratio (o/e) 1.31, 90% interval 1.21 to 1.42. Synonymous variants: 173 observed, 132.65 expected, observed/expected ratio (o/e) 1.3, 90% interval 1.15 to 1.48.
Gene-disease validity (ClinGen):
ClinGen rates the evidence that FGF3 causes each of these diseases.
deafness with labyrinthine aplasia, microtia, and microdontia (autosomal recessive): Definitive. Deafness with labyrinthine aplasia, microtia, and microdontia (LAMM) is a genetic transmission deafness syndrome.
Homologues: Orthologues: chimpanzee FGF3 (99% identical), macaque FGF3 (98% identical), guinea pig FGF3 (85% identical), dog FGF3 (84% identical), rat Fgf3 (84% identical), mouse Fgf3 (82% identical), pig FGF3 (81% identical), zebrafish fgf3 (62% identical), tropical clawed frog fgf3 (61% identical). Paralogues in human: FGF10 (33% identical), FGF5 (33% identical), FGF16 (30% identical), FGF22 (29% identical), FGF20 (29% identical), FGF9 (28% identical), FGF7 (28% identical), FGF11 (26% identical), FGF14 (24% identical), FGF6 (24% identical), FGF13 (24% identical), FGF23 (24% identical), and 9 more.
Diseases named in the same sentence as FGF3 in open-access papers:
FGF3 is named in the same sentence as 96 diseases in open-access papers, as found by Europe PMC text mining. Sharing a sentence is not in itself a finding about the gene and the disease. The quoted sentences say what the papers report.
breast cancer (29 papers, 1997 to 2025). A primary or metastatic malignant neoplasm involving the breast. "The SNP rs614367 is located in an intergenic region with multiple flanking genes, including CCND1, MYEOV, ORAOV1, FGF19, FGF4 and FGF3, all of which are potential breast cancer susceptibility genes." (PMID 30247654, 2019). "Moreover, FGF3 is associated with the onset of different types of cancer, such as human Kaposi’s sarcoma, hepatocellular carcinoma, breast cancer, Laryngeal squamous cell carcinoma, and nonsmall cell lung carcinoma." (PMID 39766329, 2024). "Dovitinib was investigated in combination with fulvestrant in postmenopausal women with hormone receptor (HR)-positive, HER2-negative, FGFR (FGFR1, FGFR2, or FGF3)-amplified breast cancer who progressed on endocrine therapy in a phase II trial." (PMID 38255923, 2024). "Prolonged estrogen deprivation in breast cancer cells can lead to upregulation of FGFR1 together with FGF3, FGF4, and FGF19 due to co-amplification of the FGFR gene and genes located in the 11q13 region." (PMID 38255923, 2024). "The FGF3 gene is amplified in breast cancer and this correlates with a lower response in patients with HER2-positive breast cancer treated with anti-HER2 therapy." (PMID 35193394, 2022). "The human FGF19 gene is amplified in breast cancer together with FGF3 and FGF4, and this correlates with worse prognosis in invasive ductal breast carcinomas, particularly in older patients with lymph node metastasis and negative ER status." (PMID 35193394, 2022). "By contrast, the FGF4 gene is amplified in breast cancer together with FGF3 and FGF15/19 as they are all part of the locus on human chromosome 11q13 that is frequently amplified in several tumours." (PMID 35193394, 2022). "In breast cancer patients with FGFR1 or FGF3 amplification, multikinase FGFR/VEGFR inhibitors have shown promising activity." (PMID 29743718, 2018). "Overall, greater than sixty WNT1/FGF3 targets (related to mitochondria, glycolysis, the EMT, and protein synthesis) that we identified in MCF7-WNT1/FGF3 cells were also transcriptionally elevated in human breast cancer cells in vivo." (PMID 26421711, 2015). "MMTV initiates mammary tumorigenesis in mice by promoter insertion adjacent to two main integration sites, namely Int-1 (Wnt1) and Int-2 (Fgf3), which ultimately activates Wnt/β-catenin signaling, driving the propagation of mammary cancer stem cells (CSCs)." (PMID 26421711, 2015). "Here, we have created a humanized model of MMTV signaling, by over-expressing WNT1 and FGF3 in human breast cancer cells, namely MCF7 cells, an ER(+) cell line." (PMID 26421711, 2015). "FGF3 was identified by its similarity with mouse fgf3/int-2, a proto-oncogene activated in virally induced mammary tumors in the mouse." (PMID 22719913, 2012). "The observation in Wnt1/Fgf3 bitransgenic mice that mammary tumor development is a stochastic event is consistent with the necessity for collaborating events during mammary tumor progression." (PMID 23131872, 2012). "However, compared to primary tumors, the frequency of FGF3/4/19 variations in R/M breast cancer was elevated in TNBC and HER2+." (PMID 40182039, 2025). "Based on these results, inhibiting STAT3 and Akt in breast cancer with higher expression levels of FGF3 could be used as a potential measure to treat breast cancer or as a complementary means for FGFR-targeted therapy." (PMID 37496658, 2023). "Those with progesterone receptor-negative primary breast cancer who have Int-2/FGF3 amplification have a five-fold greater risk of relapse." (PMID 37496658, 2023). "Additionally, it would be valuable to collect clinical samples and compare the expression levels of FGF3 in various molecular subtypes of breast cancer and normal breast tissue/benign breast lesions to explore the proportion of FGF3 overexpression in HBC." (PMID 37496658, 2023).
breast cancer (continued). "These new protein targets that we identified in MCF7-WNT1/FGF3 cells may be important for developing new strategies for the diagnosis and treatment of breast cancer." (PMID 26421711, 2015). "MKLN1 has been previously associated with childhood asthma, SORBS1 with suicide risk and childhood obesity in Hispanics, SLC1A2 with fatty acid levels, essential tremor, and other traits, EPB41L4B with wound healing, PTPN3 with cancer, and FGF3 with breast cancer and deafness." (PMID 26569114, 2015). "Therefore, we speculate that for breast cancer with high expression of FGF3, treatment against FGF3 is worth exploring and that FGF3 may be used as a drug target." (PMID 37496658, 2023). "In a Phase 1/2a study of patients with breast carcinoma harboring an amplification of FGFR1, FGF3, FGF4, or FGF19, lucitanib resulted in a disease control rate (DCR) of 100%; 50% (6/12) of patients achieved PR and 50% (6/12) of patients had SD." (PMID 38380359, 2024). "Therefore, anti-FGF3/FGFR2b therapies may benefit patients with HER2-positive breast cancer." (PMID 35193394, 2022). "FGF3 levels correlate with stage and grade, FGFR2 signalling activation and proliferation of breast cancer cells." (PMID 35193394, 2022). "For instance, FGF3/4/19 promotes resistance to HER2 inhibitors lapatinib and trastuzumab in breast cancer." (PMID 35814257, 2022). "This chromosomal region is amplified simultaneously with the 11q12–14 region, which contains other oncogenes with a role in breast cancer progression, like CCND1, FGF3, FGF4 and FGF19." (PMID 35193394, 2022). "A possible explanation for this resistance is offered by the copy number gain of FGF3 and FGF10 in this cell line, both of which have previously been defined as resistance mechanisms to BYL719 in breast cancer." (PMID 34663790, 2021). "CNAs in CCND1, FGF3, FGF4, and FGF19, which are all located in the q-arm of chromosome 11 were more likely to be detected from patients with HR+/HER2+ and HR+/HER2− breast cancer (P < 0.001)." (PMID 32695676, 2020). "The region contains CCND1 and other potential oncogenes such as FGF3, FGF4 and MYEOV and there is good evidence that this region is relevant to breast cancer." (PMID 28095868, 2017). "More specifically, we over-expressed WNT1 and FGF3 in MCF7 cells, an ER(+) human breast cancer cell line." (PMID 26421711, 2015). "In that study Wnt1 and Fgf3 were activated by MMTV in 52% and 14% in C3H mammary tumors, respectively where as in the HOG derived tumors they were activated in 6% and 0%, respectively." (PMID 23131872, 2012). "First, a large percentage of mammary tumors derived from MMTV-infected wild type mice have “hits” at both Wnt1 and Fgf3; it is likely that additional genes are activated in these tumors." (PMID 21274409, 2010). "In addition to the FGF3 locus (int-2 in mice), high-throughput analysis of the MMTV insertional mutagenesis identified an activated FGF pathway in 67% of the mammary tumors with virus common insertion sites near FGFR1 and FGFR2." (PMID 35996584, 2022). "Murine FGF3 gene was initially termed int-2, named after its locus, which harbored approximately 50% of mouse mammary tumor virus (MMTV) insertion sites with high incidence of mammary carcinomas." (PMID 35996584, 2022). "Thus, to develop a humanized model of MMTV signaling, we over-expressed WNT1 and FGF3 in MCF7 cells, an ER(+) human breast cancer cell line." (PMID 26421711, 2015). "Thus, in order to create a humanized model of MMTV signaling, we recombinantly over-expressed WNT1 and FGF3 in MCF7 cells, an ER(+) human breast cancer cell line." (PMID 26421711, 2015). "For instance, int-2/fibroblast growth factor-3 (FGF3), an oncogene that is recurrently amplified in human breast tumors, first came to prominence because of its dysregulation resulting from a shared integration site of mouse mammary tumor virus in murine models of breast cancer." (PMID 29941549, 2018).
breast cancer (continued). "Other studies show no expression of FGF3 and FGF4 in human breast cancers but expression of all other FGFs in at least a small proportion of breast cancers." (PMID 11953856, 2002).
deafness (9 papers, 2011 to 2025). An inherited or acquired condition characterized by the complete loss of the ability to hear from one or both ears. "The proband with the FGF3 variant is a 6-year-old male with bilateral congenital profound deafness whose temporal bone CT scan showed bilateral labyrinthine aplasia." (PMID 38947059, 2024). "Pathogenic variants in FGF3 cause deafness with LAMM (Labyrinthine Aplasia, Microtia, and Microphthalmia; OMIM 610706), an autosomal recessively-inherited syndrome characterized by missing inner ear structures as well as small external ears and teeth." (PMID 38947059, 2024). "Homozygous variants in FGF3 have been associated with deafness, accompanied by inner ear agenesis, microtia, and microdontia." (PMID 33187236, 2020). "SLC26A4 and FGF3, two genes that have been previously reported to be associated with deafness and Mondini malformation, were included in our targeted NGS analysis." (PMID 26011067, 2015). "We conclude that the manifestations of recessive FGF3 mutations range from fully penetrant LAMM syndrome to deafness with residual inner ear structures and, by extension, with minimal syndromic features." (PMID 21306635, 2011). "We identified homozygous FGF3 mutations co-segregating with deafness in three families (PKDF295, PKDF817 and PKDF887)." (PMID 21306635, 2011). "Taken together, our results show that the manifestations of recessive FGF3 mutations can involve nearly non-syndromic deafness with variable inner ear structural development." (PMID 21306635, 2011). "Therefore, we conclude that the manifestations of recessive FGF3 mutations range from fully penetrant LAMM syndrome to deafness with residual inner ear structures and, by extension, with minimal syndromic features, an observation with implications for cochlear implantation candidacy." (PMID 21306635, 2011). "We detected FGF3 (p.Arg165Gly) and GREB1L (p.Cys186Arg), variants of uncertain significance in two recognized genes for deafness, and PBXIP1(p.Trp574*) in a candidate gene." (PMID 38947059, 2024). "In addition to FGF3, mutations in the FGF10 and FGFR2b have been associated with a syndromic form of deafness known as lacrimo‐auriculo‐dento‐digital (LADD) syndrome (OMIM 149730)." (PMID 36934406, 2023). "In this regard, mutations of either LRTOMT or FGF3 should be considered when incompletely characterized nonsyndromic deafness is found to be linked to genetic markers of the DFNB63 locus on chromosome 11q 13.2 -q13.3." (PMID 21306635, 2011). "Therefore, we conclude that the phenotypic spectrum of recessive FGF3 mutations range from fully penetrant LAMM syndrome to deafness with residual inner ear structures and absent or minimal syndromic features." (PMID 21306635, 2011).
bladder cancer (7 papers, 2008 to 2023). "Dysregulation of fibroblast growth factors, especially FGF1 and FGF3, have been associated with the risk of bladder cancer." (PMID 35888106, 2022). "FGF3 has been repeatedly found amplified in bladder cancer and its up-regulated expression has been associated with tumor's malignant clinical phenotypes." (PMID 35841413, 2022). "FGF pathway genes, including FGF3, FGF4 and FGF8, are common targets of MMTV integration and FGFR3 mutations have been reported in 41% of bladder cancers." (PMID 18840272, 2008). "However, to the best of our knowledge, the role of FGF4 in bladder cancer is limited, despite its prominent role in MAPK pathway activation linked with FGF1 and FGF3." (PMID 35888106, 2022). "The role of FGF1 and FGF3 is evident in bladder cancer; however, the role of FGF4 is vague." (PMID 35888106, 2022).
breast tumors (5 papers, 2018 to 2023). "Most of the induced breast tumors are mainly at wnt1 and fgf3 sites by MMTV infection in wild-type mice." (PMID 32432040, 2020). "Consequently, these cells are the ones that eventually give rise to breast tumors as a result of insertional mutagenesis, where viral enhancer elements end up activating expression from growth promoting genes, such as Wnt1 and Fgf3." (PMID 37243196, 2023). "HR+ breast tumors regardless of HER2 status (HR+/HER2+ and HR+/HER2−) were more likely to harbor CNAs in CCND1, FGF3, FGF4, and FGF19, which colocalizes in chromosome 11q13.3." (PMID 32695676, 2020).
ovarian carcinoma (5 papers, 1993 to 2020). A malignant neoplasm originating from the surface ovarian epithelium. "For example, Cole C. with the co-authors found the inhibition of FGFR2 and/or FGF-3 and -7 substantially reduced the proliferation of ovarian cancer cells and reduced the IC50 for cisplatin in vitro." (PMID 31948066, 2020). "Estimation of FGF-3 oncogene amplification in DNA samples extracted from paraffin embedded sections of 136 ovarian cancer samples was carried out by a quantitative PCR method." (PMID 8494710, 1993). "Studies have also shown amplification of FGF3 in nasopharyngeal carcinoma, ovarian cancer, endometrial carcinomas, lung cancer, and oral cancer, which may be important for neoplastic transformation and tumor progression." (PMID 22719913, 2012). "The data combine to suggest that FGF-3 is an indicator of aggressiveness of ovarian cancer." (PMID 8494710, 1993).
hepatocellular carcinoma (4 papers, 2012 to 2022). A malignant tumor that arises from hepatocytes. "Targetable FGF3 amplification was associated with a poorer prognosis and lung metastasis in hepatocellular carcinoma." (PMID 35982973, 2022). "Critical genes encoded by this region include CCND1, FGF3, FGF4, which are involved in cell-cycle regulation and tumor cell proliferation in oral squamous cell carcinoma, hepatocellular carcinoma, and ESCC11,54–56." (PMID 34285259, 2021).